FMR1 (fragile X messenger ribonucleoprotein 1)
Diseases named in the same sentence as FMR1 in open-access papers (continued):
Sharing a sentence is not in itself a finding about the gene and the disease.
autism (230 papers, 2009 to 2026). Persistent deficits in social interaction and communication and interaction as well as a markedly restricted repertoire of activity and interest as well as repetitive patterns of behavior. "Together, these up- and downregulated targets, majority of which are linked to autism and ID, underscore distinct molecular mechanisms through which Syngap+/− and Fmr1−/y mouse models show impaired neurodevelopment, synaptic function, and cognitive outcomes." (PMID 40295099, 2025). "Similar findings were observed by others, namely, increased D2 receptor binding density in the ventral striatum in Shank3-deficient mice, and a similar trend was observed in the Fmr1 mouse model of autism." (PMID 39654001, 2025). "For instance, studies have identified a strong correlation between mutations in the FMR1 gene and autism." (PMID 39734494, 2024). "We also observed decreased activity blocked by TTX and a decrease in the expression of NMDA receptor subunit GRIN2B, a gene previously associated with autism, in our FMR1 KO and FXS patient lines iPSC-derived neurons." (PMID 37834379, 2023). "A potential clue is that mice that lack certain autism-linked genes, such as Fmr1 and Cx3cr1, show impaired pruning and that ASD and SZ are linked with abnormal microglia." (PMID 35221938, 2022). "Similar deficiencies in sociability were identified in Fmr1 KO mice, a well-known model of autism, as well as in most autistic patients." (PMID 35505150, 2022). "For instance, in the rodent, silencing Fmr1, a gene linked to fragile X syndrome, which is often correlated with autism, leads to an upregulation in BMP type II receptor and its signaling kinase." (PMID 35221938, 2022). "The objective was to compare the CGG repeat variants in FMR1 gene among three correlating cohorts of ID, autism and idiopathic POI." (PMID 36618123, 2021). "The autism subjects were further subdivided in two groups: a group of six with autism caused by a fragile X mutation (FMR1-FM) and a group of seven with autism caused by a 15q11–q13 duplication (dup15q)." (PMID 34185214, 2021). "FXS, caused by mutations in the FMR1 gene, is one of the most prevalent causes of monogenic autism representing about 2%–5% of all ASD diagnoses." (PMID 33484493, 2021). "This study determined if complete FMR1 mRNA silencing from FM alleles and/or levels of FMR1 mRNA (if present) in blood are associated with intellectual functioning and autism features in FXS." (PMID 31073396, 2019). "The most direct evidence comes from monogenic, syndromic forms of autism, many of which are caused by lost or reduced function in genes, including eIF4E, FMR1, PTEN, NF1, TSC1, TSC2 and PRKCB1, that negatively regulate the pathway or its subsystems." (PMID 31548888, 2019). "This is the first study to demonstrate that the presence of incomplete FMR1 mRNA silencing in blood is significantly associated with more severe autism features (predominantly social communication difficulties) in FM-only males." (PMID 31073396, 2019). "Fragile X mental retardation 1 (FMR1) is an evolutionary conserved RNA binding protein implicated in autism." (PMID 30544507, 2018). "Translation has been an important topic in ASD primarily because of work on syndromic forms of autism related to mutations in FMR1, TSC1/2, and PTEN, as well as the important cap-dependent translation gene EIF4E." (PMID 28649314, 2017). "This protein family received its name from FMR1, the Fragile X mental retardation protein 1, which is associated with autism and mental retardation." (PMID 27509095, 2016). "Several genes that often occur in minority polymorphisms in autism (FMR1, Tuberous Sclerosis complex 1 and 2 -TSC1, TSC2, and phosphatase and tensin homolog-PTEN) and the STEP protein that is upregulated in FXS65 are associated with these pathways." (PMID 27212113, 2016). "FMR1 mutation or deletion has shown autism-like behaviors such as impaired social activity, anxiety, and reduced behavioral flexibility." (PMID 27184741, 2016).
autism (continued). "Approximately one-third of patients with FXS are eventually diagnosed with autism spectrum disorder, and it is estimated that up to 6-8% of children diagnosed with autism carry mutations in the X-linked FMR1 gene." (PMID 24205018, 2013). "FXS is caused by mutations in the Fmr1 and/or Fxr2 gene, the autosomal homolog of Fmr1, and is characterized by mental retardation and occasionally autism and epilepsy." (PMID 22016787, 2011). "Fragile X syndrome is caused by loss of function of the fragile X mental retardation 1 (FMR1) gene and shares multiple phenotypes with autism." (PMID 21548960, 2011). "Mice with deletion of the fragile X mental retardation 1 (Fmr1) gene are used to model autism because loss of Fmr1 gene function causes Fragile X Syndrome (FXS) and many people with FXS exhibit autistic-like behaviors." (PMID 20300527, 2010). "Further, elevated levels of FMR1 mRNA lead to RNA gaining a toxic function, which may contribute to an increased risk of neurodevelopmental problems, including autism." (PMID 40243429, 2025). "Rac1 and Fmr1, which regulate Retro-I in Drosophila, are high-risk genes for autism." (PMID 36897069, 2023). "In addition to Fmr1, several other genes at high risk for autism encode synaptic proteins and affect synapse formation, maturation, and synaptic connections." (PMID 35530178, 2022). "FMR1 deficiency has been associated with numerous co-occurring conditions including, but not limited to, intellectual and emotional disabilities ranging from learning problems to mental retardation, and mood instability to autism." (PMID 35549943, 2022). "A work in autism showed that the reduction in social interactions caused by partial Fmr1 protein deficiency occurs in a mixed FVB/N-129/OlaHsd background in a similar manner then in partial serotonin transporter (Slc6a4-/y) deficient mice and not in C57BL/6J animals." (PMID 34473777, 2021). "Whilst variants affecting the related FXR1 gene confer risk to schizophrenia, bipolar disorder, and autism, the genetic link between FMR1 and psychiatric disorders derives from enrichment of association within the gene targets of FMRP (among which the fragile-X family genes themselves are included)." (PMID 34883502, 2020). "Interestingly, secondary findings, that is, CNVs encompassing genes of interest (here defined as genes associated with autism or expressed in the brain), were discovered in the patient with the FMR1 mutation." (PMID 30647996, 2019). "Loss of function in multiple genes that negatively regulate mTOR, including TSC1, TSC2, PTEN, NF1, and FMR1, has been linked to syndromic autism with increased head size and high rates of seizures; both of these traits are also found in mice heterozygous for AMBRA1 loss of function." (PMID 31687209, 2019). "Loss of function of Fmr1 is one of the leading genetic causes of Fragile X and autism." (PMID 30087606, 2018). "Moreover, we demonstrate that hyperactivity of ADCY1-directed neuronal signalling is causative for autism-related core behavioural abnormalities in the Fmr1 KO mouse model of FXS, which can be reversed by genetic and pharmacological reduction of ADCY1." (PMID 28218269, 2017). "Intriguingly, recent evidence indicates that disrupted mGluR5-Homer1 interactions in a mouse model of FXS (Fmr1-/Y mice) underlies the development of phenotypes relevant to autism, including hippocampal protein synthesis, neocortical circuit dysfunction and behavior." (PMID 22558107, 2012). "Mutations in FMR1, known to cause syndromic autism, may also contribute to the etiology of high-functioning, non-syndromic ASD, particularly in women." (PMID 22738402, 2012).
autism (continued). "According to previous studies, Fmr1-/y mice are a typical mouse model of genetic defects associated with autism, and LPS-induced autistic mice could represent an autism mouse model, which may be mainly caused by environmental factors via maternal immune activation (MIA)." (PMID 35869039, 2022). "Since the Fmr1 gene has been identified as an autism-related gene and the most common cause of autism, modulation of mGluRs for the treatment of FXS might also be beneficial for autism, which is also supported by the observation that MPEP blocked repetitive features in a mice model of autism." (PMID 22942876, 2012). "FPT demonstrates anti-seizure, anxiolytic, and prosocial properties, as well as reduces stereotypic movements in Fmr1 knockout mice, a model for autism." (PMID 42026829, 2026). "We previously demonstrated that the maternal immune activation model of autism shows similar aversion to social touch as Fmr1 KO mice." (PMID 40382316, 2025). "In this manuscript, the authors have systematically analyzed translating mRNAs of hippocampal CA1 neurons in two mouse models of autism: Syngap and Fmr1." (PMID 40295099, 2025). "Both Syngap+/− and Fmr1−/y mice are models of autism and ID; however, they express different plasticity phenotypes in hippocampal CA1." (PMID 40295099, 2025). "Knockdown of FMR1 in zebrafish larvae resulted in autism-like behavior similar to the valproic-acid treated zebrafish larvae." (PMID 38542432, 2024). "The inactivation of the X chromosome-linked FMR1 gene causes the development of fragile-X syndrome (FXS), the most common cause of inherited mental retardation and possibly autism." (PMID 38132127, 2023). "Together, these results indicates that ASO-Tau treatment attenuates autism-like behaviors in Fmr1 KO mice." (PMID 37936174, 2023). "The fragile X messenger ribonucleoprotein 1 (Fmr1) knockout (KO) mouse is the oldest and one of the most studied genetic mouse models used in autism research." (PMID 37238724, 2023). "Our analyses also indicate that a substantial proportion of differentially expressed genes are deregulated at the NPC and neuronal stages and that a considerable proportion of downregulated genes in FMR1 KO cells includes autism-related genes and FMRP targets." (PMID 37834379, 2023). "Mutations in the FMR1 gene due to the CGG repetition can result in several conditions, e.g., ID, FXPOI, FXTAS, autism, Parkinson’s disease, developmental delays, other cognitive deficits, and even fragile X-associated neuropsychiatric disorders (FXAND)." (PMID 37420260, 2023). "Purine receptor antagonists produce symptomatic improvements in the core symptoms of autism in fragile X messenger ribonucleoprotein 1 (FMR1) knock-out mouse models." (PMID 37932739, 2023). "By demonstrating that Tau reduction prevents autism-like phenotypes possibly through modulating the P38/MAPK signaling in Fmr1 KO mice, this study provides strong evidence that Tau is a new target for FXS therapeutics." (PMID 37936174, 2023). "Fmr1 is a strong candidate gene associated with ASD, and its deficiency was implicated in autism development." (PMID 35783275, 2022). "Behavioural studies of auditory function in rodent models of ASD highlight another difference between Fmr1 models and other autism models." (PMID 36042393, 2022). "Increased resting gamma power in both Fmr1 and other autism models and increased evoked gamma power in Fmr1 models but decreased across other models match well with recordings from human studies." (PMID 36042393, 2022).
autism (continued). "To further evaluate the association between SARM1 and autism, we checked the expression level of SARM1 protein in two autism mouse models (Fmr1-/y, LPS-induced autistic mice)." (PMID 35869039, 2022). "DNA methylation status of the CGG repeats in the FMR1 gene promoter at birth is predictive of later intellectual function and autism features." (PMID 34445048, 2021). "The fragile X syndrome is a frequent syndromic form of intellectual disability (ID) and autism, caused by an expansion of the CGG-repeat in the 5-’UTR of the fragile X mental retardation 1 (FMR1) gene, into the full mutation range (> 200 repeats)." (PMID 33510257, 2021). "Shank2 and Fmr1 mutant mouse models of autism display hyperactivity that is increased by the administration of MPH." (PMID 33785025, 2021). "Among the genetic causes, mutations in the FMR1 gene, which cause FXS, are the leading known genetic cause of autism." (PMID 34926684, 2021). "This is consistent with several previously published mouse models related to autism, including Chd8+/−, 22q11.2, Fmr1, Itgb3, En2, Nrxn1a, and Shank3." (PMID 33757588, 2021). "On the contrary, expansions of the FMR1 gene >200 CGG repeats lead to a loss of FMRP protein and autism, but the premutation causes PD, with the RNA found in foci in the brain of FXTAS cases." (PMID 32785033, 2020). "It is estimated that 30% of FXS cases have autism and 2–6% of all cases with autism carry FMR1 repeat expansions." (PMID 32785033, 2020). "Only one study has specifically explored the relationship between FMR1 mRNA levels in blood and autism features in males with FXS (n = 63; 38% PM/FM mosaic), and provided appropriate statistical analyses at group level." (PMID 31073396, 2019). "In an Fmr1 KO model of autism, two cerebellar nuclei were found to be decreased in size; immunohistochemistry unraveled a loss of neurons accounting for the shrinkage." (PMID 30853900, 2019). "In support of our findings, separate studies have provided evidence for astrocytic activation in the cerebellum of Fmr1 KO mouse and in patients with autism." (PMID 31200759, 2019). "A reduced association of mGlu5 receptors with long Homer isoforms has been reported in mouse models of monogenic autism, such as Fmr1 and Shank3 knockout mice." (PMID 29615849, 2018). "Fragile-X typically arises via CGG trinucleotide repeats in its promotor region of Fmr1, the X-linked gene that encodes FMRP and a leading monogenic cause of inherited learning disability and autism." (PMID 29899064, 2018). "In this study, autistic-like behaviors were described in 27% of unrelated patients; however, only two patients were diagnosed with autism before the FMR1 DNA testing was performed." (PMID 28751920, 2017). "Women with the FMR1 premutation also exhibit increased personality features consistent with the broad autism phenotype and decreased sensitivity to biological motion." (PMID 28835209, 2017). "Together, these results demonstrate that genetic deletion of Adcy1 in Fmr1 KO mouse rescues several well-characterized autism-related symptoms." (PMID 28218269, 2017). "Pre-delivery treatments with Oxt or with a selective NKCC1 inhibitor in a model of autism, the valproate rat, and in a model of fragile X, the Fmr1−/− mouse, were shown to rescue the altered GABA balance in pups and social behavioral deficits in adults." (PMID 27052180, 2016). "The Fmr1 knockout is the oldest, and one of the most studied genetic mouse models used in autism research." (PMID 25705365, 2015). "Mutation of FMR1 (the X-linked gene encoding FMRP) results in FXS, the leading cause of inherited intellectual disabilities and autism." (PMID 24806451, 2014). "An anatomical abnormality of neurons from brains of individuals with FXS, autism, and Fmr1 knockout (KO) mice are dendrites with an overabundance of immature long, thin spines." (PMID 23803181, 2013). "FMR1 KO mice exhibit elevated cortical spine densities similar to those observed in autism and Fragile X syndrome." (PMID 24151553, 2013).
autism (continued). "Although some of the genes studied are known to cause syndromic ASD (e.g. FMR1, TSC1, TSC2, UBE3A), their possible role in non-syndromic autism has been unclear." (PMID 22558107, 2012). "We have previously found reduced expression of the protein product of FMR1 (FMRP) in vermis of adults with autism." (PMID 21548960, 2011). "The goal of this study was to compare brain activation patterns of the pan-5-HT1R agonist FPT to NLX-112, a highly selective 5-HT1AR full agonist (pEC50 = 7.5) which also prevents seizures in Fmr1 knockout mice, to help establish therapeutic mechanisms in autism." (PMID 42026829, 2026). "Therefore, the rescuing effect of Tau reduction on autism-like phenotypes in Fmr1 KO mice is unlikely through reversing Per1 expression and periodic activity defect." (PMID 37936174, 2023). "Our data indicate that Tau reduction prevents autism-like phenotypes in Fmr1 KO mice." (PMID 37936174, 2023). "In our study, upregulation of SARM1 protein was found in the brain tissue of two autism mouse models, Fmr1 KO mice and an LPS-induced MIA mouse model, which could represent a genetic model and an environmental model of ASD." (PMID 35869039, 2022). "A study found that Htt-KO mice exhibited autism-like behavioral characteristics like Fmr1-KO mice and that the mitochondrial fusion phenotype could be rescued by enhancing the Htt expression." (PMID 36474209, 2022). "Given the comorbidity of FX and autism, Fmr1 KO mice (FX mice) represent a well-defined genetic model that can provide neural circuit-level insights into autism, especially considering the vast diversity of phenotypes and manifestations observed in autism spectrum disorders (ASDs)." (PMID 34093132, 2021). "Similarly, deletion of Fmr1 gene in PCs (L7-Fmr1; a model for syndromic autism) attenuates eyeblink conditioning by altering LTD profile." (PMID 31507382, 2019). "Future research aiming to disentangle autism features and social anxiety and their relationship with molecular mechanisms, such as FMR1 mRNA, is warranted, as this may have implications for treatments that target these specific behaviours." (PMID 31073396, 2019). "For example, polymorphisms in the FMR1 gene have been reported to be associated with autism, however, no consistent association between FMR1 polymorphisms and autism has been demonstrated." (PMID 31824553, 2019). "Moreover, multiple autism-like behavioral phenotypes of Fmr1 KO mice are able to be rescued by removal of S6K1, a downstream kinase of mTOR." (PMID 31849609, 2019). "Given the similarity across the fragile X spectrum in phenotypic expression with regard to clinical features such as autism and other behavioral issues, increased sensory dysregulation may also be present in individuals with an FMR1 premutation." (PMID 30233641, 2018). "The increased prevalence of autism symptomology in the FMR1 premutation may be due to mRNA toxicity." (PMID 30233641, 2018). "Furthermore, pragmatic language difficulties comprise a principal feature of autism and the broad autism phenotype, both of which are elevated in women with the FMR1 premutation." (PMID 28835209, 2017). "Accounting for 2–6% of all cases of autism, FXS is a neurodevelopmental disorder that is associated with an expansion in a CGG trinucleotide repeat element in the 5′ UTR of the Fragile X Mental Retardation 1 (FMR1) gene." (PMID 26483618, 2015). "To conclude, in all three replication samples, we confirmed the association of the 8‐SNP model, derived from the broader fragile X gene family (FMR1, FXR1, FXR2, FMR2), with autism‐related behaviors, underlining the phenotypical continuum of these traits across health and disease." (PMID 26612855, 2015). "However, whether Tau reduction can prevent autism-like features in Fmr1 KO mice and become a novel strategy for FXS treatment remain unknown." (PMID 37936174, 2023).